NUCB2 (nucleobindin 2)
Diseases named in the same sentence as NUCB2 in open-access papers (continued):
Sharing a sentence is not in itself a finding about the gene and the disease.
breast carcinoma (20 papers, 2013 to 2025). "NUCB2 has been identified as a recurrence-associated gene that enhances tumor cell proliferation, migration, and invasion in breast cancer." (PMID 40964608, 2025). "In our previous study, Suzuki and I found that NUCB2 is highly expressed in breast cancer tissues and metastatic lymph nodes and is associated with poor prognosis." (PMID 37277807, 2023). "NUCB2 has been associated with poor prognosis in breast cancer, prostate cancer, endometrial carcinoma, and bladder cancer, while low expression levels of SLC7A2 in ovarian cancer were associated with a positive prognosis." (PMID 37894871, 2023). "In this current study, we investigated the molecular mechanism underlying the role of NUCB2 in breast cancer." (PMID 37277807, 2023). "Upregulation of Nucb2 expression was also significantly associated with lymph node metastasis in breast carcinoma cells." (PMID 34073612, 2021). "They found NUCB2/NESF-1 to be a gene associated with the recurrence of estrogen receptor-positive breast carcinoma patients (n = 5)." (PMID 34361082, 2021). "Recent studies indicate that a high level of nesfatin-1/Nucleobindin-2 (NUCB-2) is associated with poor outcome and promotes cell migration in breast cancer and prostate cancer." (PMID 27150059, 2016). "We first found that NUCB2 overexpression is potentially caused by acetylation in breast cancer." (PMID 37277807, 2023). "Furthermore, we demonstrated that the positive expression of NUCB2 in primary breast tumors is an independent risk factor for the poor prognosis of breast cancer patients." (PMID 37277807, 2023). "NUCB2/nesfatin-1 contributes to the development and progression of various cancers, such as prostate, colon, and breast cancers, and the underlying mechanism may be related to its ability to promote cell proliferation, migration, and invasion." (PMID 36585713, 2022). "Thus, NUCB2/Nesfatin-1 might be utilized as a diagnostic tool and also used in cancer therapy for breast cancer in the future." (PMID 37277807, 2023). "In our previous study, we highlighted the crucial role of NUCB2 in breast cancer regulation, particularly in lymph node metastasis." (PMID 37277807, 2023). "In conclusion, our study demonstrates that NUCB2/Nesfatin-1 upregulates cholesterol synthesis, promoting breast cancer metastasis." (PMID 37277807, 2023). "Our results provide valuable insight into NUCB2/Nesfatin-1 as a regulator of cholesterol synthesis and a potential drug target for breast cancer therapy." (PMID 37277807, 2023). "In all, till now we first reported that NUCB2 promotes metastasis via the secreted fragment, Nesfatin-1 in breast cancer." (PMID 37277807, 2023). "We analyzed the serum concentration of Nesfatin-1 in breast cancer patients and healthy controls and found that Nesfatin-1 concentration was higher in patients, corresponding to overexpression of NUCB2 in breast cancer tissues." (PMID 37277807, 2023). "We also treated NUCB2 knockdown the breast cancer cell lines with purified Nesfatin-1 and found that the expression of SREBP2 and HMGCR was upregulated in a dose-dependent manner." (PMID 37277807, 2023). "Our results showed that the average concentration of Nesfatin-1 in breast cancer patients was significantly higher than that in healthy controls (P < 0.01), which was consistent with the high expression of NUCB2 in breast cancer tissues." (PMID 37277807, 2023). "Among the proteins identified, NUCB2 was found to be highly expressed in paired primary breast tumors and metastatic lymph nodes, and was positively correlated with poor survival of breast cancer patients." (PMID 37277807, 2023). "In this study, we further investigated the expression of NUCB2 in breast cancer by analyzing the TCGA database and found that NUCB2 expression was significantly higher in breast cancer tissues (n = 1097) than in normal tissues (n = 114) (P < 0.001)." (PMID 37277807, 2023).
breast carcinoma (continued). "Nesfatin-1 also rescued the breast cancer cells' stemness in NUCB2 silenced cell lines, as demonstrated by the colony formation assay." (PMID 37277807, 2023). "Taken together, our data indicate that NUCB2/Nesfatin-1 regulates cholesterol biosynthesis via the HMGCR/SREBP2 axis in breast cancer." (PMID 37277807, 2023). "To preliminarily explore the mechanism of high expression of NUCB2 in breast cancer, we analyzed the potential acetylation sites in NUCB2 and the acetyltransferases involved using the CUCKOO database." (PMID 37277807, 2023). "Above findings suggest that Nesfatin-1 is the potentially crucial component for NUCB2 to exert its biological effects in breast cancer." (PMID 37277807, 2023). "NUCB2/Nesfatin-1 was found to be overexpressed in the breast cancer patients, and its overexpression was positively correlated with poor prognosis." (PMID 37277807, 2023). "It is necessary to determine the eraser, writer, and reader so as to clearly clarify the molecular mechanism of high expression of NUCB2 in breast cancer." (PMID 37277807, 2023). "To explore the mechanism of NUCB2 overexpression in breast cancer, we used the CUCKOO database to predict potential acetylated sites and the acetyltransferases involved." (PMID 37277807, 2023). "Taken together, our results suggest that NUCB2/Nesfatin-1 promotes the synthesis of cholesterol in breast cancer cells, thereby enhancing cell invasion and metastasis." (PMID 37277807, 2023). "To investigate the clinical significance of NUCB2, we collected serum samples from 40 healthy donors and 40 breast cancer patients and measured the concentration of Nesfatin-1, a cleavage product of NUCB2, using ELISA." (PMID 37277807, 2023). "Mechanistically, NUCB2/Nesfatin-1 upregulated cholesterol synthesis via the mTORC1 signal pathway, contributing to breast cancer migration and metastasis." (PMID 37277807, 2023). "Transwell migration and Matrigel invasion assays were conducted, and nude mouse lung metastasis models were established to examine the effect of NUCB2/Nesfatin-1 on breast cancer metastasis in vitro and in vivo." (PMID 37277807, 2023). "Our study defines the function of NUCB2/Nesfatin-1 in breast cancer and sheds light on potential therapeutic targets for this disease." (PMID 37277807, 2023). "Patients with high NUCB2/Nesfatin-1 expression have significantly poor overall survival and increased recurrence rates in breast cancer." (PMID 37277807, 2023). "Subsequently, we generated NUCB2 knockdown breast cancer cell lines and found that these cells exhibited reduced invasion and metastasis." (PMID 37277807, 2023). "Our findings suggest that NUCB2/Nesfatin-1 promotes cholesterol synthesis in breast cancer cells, thereby enhancing cell invasion and metastasis." (PMID 37277807, 2023). "The presence of NUCB2/NESF-1 detected by immunohistochemistry (IHC) was higher in breast carcinoma compared to benign changes in the glandular tissue in the breast (mastopathy; control)." (PMID 34361082, 2021). "Further research showed that estradiol treatment of the MCF-7 breast cancer cell line for 3 days significantly increased the Nucb2 expression level." (PMID 34073612, 2021). "As a result, these cells seem to be a controversial model to investigate the role of NUCB2 in breast cancer invasion." (PMID 34361082, 2021). "An increasing number of studies indicated that NUCB2 acts as a tumour promoter enhancing tumourigenesis and metastasis in breast cancer and renal cell carcinoma (RCC)." (PMID 30055641, 2018). "In breast cancer, NUCB-2 plays an important role in the metastasis of breast cancer cell lines and is a potent prognostic factor for primary breast carcinoma." (PMID 27150059, 2016). "Notably, NUCB2/nesfatin-1 expression has been detected at both mRNA and protein levels in adrenocortical carcinoma and breast cancer cells." (PMID 40964608, 2025). "NUCB2 enhanced breast cancer metastasis via upregulating cholesterol synthesis." (PMID 39309426, 2024).
breast carcinoma (continued). "Our findings suggest that NUCB2/Nesfatin-1 overexpression in breast cancer may serve as a potential biomarker for poor prognosis and tumor aggressiveness." (PMID 37277807, 2023). "The results suggested that NUCB2 may be overexpressed in breast cancer cells potentially through protein acetylation." (PMID 37277807, 2023). "Here, we studied whether NUCB2/Nesfatin-1 promotes breast cancer metastasis through reprogramming cholesterol metabolism." (PMID 37277807, 2023). "Database analysis suggested that NUCB2/Nesfatin-1 might be acetylated in breast cancer, which was confirmed by treating the breast cancer cells with acetyltransferase inhibitors." (PMID 37277807, 2023). "Therefore, our results suggest that NUCB2 promotes migration and invasion in breast cancer cells in vitro, likely through EMT." (PMID 37277807, 2023). "NUCB2 was potentially acetylated, leading to high expression in breast cancer." (PMID 37277807, 2023). "Therefore, NUCB2/Nesfatin-1 is suggested to be a new prognostic and predictive marker in breast cancer." (PMID 37277807, 2023). "To further confirm the role of NUCB2 in breast cancer, we treated the breast cancer cells with exogenous Nesfatin-1 protein at doses of 400 pg/mL or 1000 pg/mL, which was shown to be less toxic, and conducted migration and invasion assays on stable clones with NUCB2 knockdown." (PMID 37277807, 2023). "The expression of NUCB2/NESF-1 was localized in the cytoplasm of breast cancer cells." (PMID 34361082, 2021). "Interestingly, analysis of microarray experiments of gene expression profiling showed that the Nucb2 gene is among the genes involved in the recurrence in estrogen receptor (ER)-positive breast carcinoma patients after surgery." (PMID 34073612, 2021). "Interestingly, the survival analysis with an online analysis tool on 2032 breast cancer cases indicated that a good prognostic effect of high NUCB2 expression was related to longer OS." (PMID 34361082, 2021). "In vitro studies showed that NUCB2/NESF-1 knockdown with siRNA or shRNA in breast cancer (MCF-7, SKBR-3), bladder cancer (T24, 5637), glioblastoma (U251, U87), endometrial cancer (Ishikawa and Sawano), and thyroid cancer (TPC-I, KI) cell lines resulted in the inhibition of cell proliferation." (PMID 34361082, 2021). "Moreover, it was demonstrated that breast cancer patients with high NUCB2/NESF-1 expression had a significantly poorer overall survival (OS)." (PMID 34361082, 2021). "NUCB2 is a potential biomarker for breast cancer metastasis." (PMID 32929364, 2020). "In the positive control, NUCB2 was mainly positive in the cytoplasm of breast carcinoma cells." (PMID 24422979, 2013). "We also analyzed the expression of NUCB2 and SREBP2/HMGCR in breast cancer patients in the TCGA database and found a positive correlation between them." (PMID 37277807, 2023). "Reprogramming lipid metabolism for tumor metastasis is essential in breast cancer, and NUCB2/Nesfatin-1 plays a crucial role in regulating energy metabolism." (PMID 37277807, 2023). "Our findings demonstrate that the NUCB2/Nesfatin-1/mTORC1/SREBP2 signal pathway is critical in regulating cholesterol synthesis, essential for breast cancer metastasis." (PMID 37277807, 2023). "To investigate the role of NUCB2/Nesfatin-1 in breast cancer, we used shRNA to knock down NUCB2 expression in BT-549 and MDA-MB-231 cells, which express NUCB2/Nesfatin-1 at high levels." (PMID 37277807, 2023). "We then treated BT-549 and MDA-MB-231 breast cancer cell lines with C646, a CREBBP inhibitor, and found that the protein level of NUCB2 decreased in a dose-dependent manner with increasing concentrations of C646." (PMID 37277807, 2023). "In all, our findings suggest that NUCB2/Nesfatin-1 regulates cholesterol synthesis by improving SREBP2 and HMGCR abundance via the mTORC1 pathway, resulting in high metastasis ability in breast cancer both in vitro and in vivo." (PMID 37277807, 2023).
breast carcinoma (continued). "We report NUCB2/NESF-1 expression and its relation to clinicopathological parameters in breast cancer cells." (PMID 36012443, 2022). "The expression of NUCB2/NESF-1 was also examined at the mRNA and protein levels in breast cancer cell lines." (PMID 36012443, 2022). "In vitro studies revealed that NUCB2/NESF-1 increases invasion, migration, and proliferation in the colon, bladder, papillary thyroid, endometrial, renal, breast cancer cells, and glioblastoma." (PMID 34361082, 2021). "Further analysis of their expression in human breast cancer samples of a published UNC dataset showed the association of DMBT1, but not NUCB2, expression with patient survival." (PMID 40796724, 2025). "We found that lysine at multiple locations of NUCB2 may be acetylated, and the acetyltransferases involved are mainly CREBBP, which has been reported to be activated in breast cancer and to elevate acetylation of many substrates." (PMID 37277807, 2023). "We found a new pattern of action for NUCB2 in breast cancer metastasis, and the further mechanism by NUCB2 activates mTORC1/SREBP2/HMGCR is not clear." (PMID 37277807, 2023). "We evaluated the expression of NUCB2 in breast cancer tissues in our current research (data not published yet)." (PMID 34361082, 2021). "Nucleobindin 2 (NUCB2) protein, a novel oncoprotein, is overexpressed in breast cancer." (PMID 24422979, 2013). "Nucleobindin 2 (NUCB2) abnormal expression has been reported in gastric cancer and breast cancer." (PMID 23958433, 2013). "Thus we intended to explore whether NUCB2 regulates SREBP2 expression through mTORC1, mediating cholesterol synthesis and leading to malignant phenotype in breast cancer." (PMID 37277807, 2023).
Anorexia (14 papers, 2009 to 2024). Lack of desire to eat (loss of appetite). "It was also suggested that NUCB2/NESF-1 expressed in the parvocellular region contributed to anorexia by secreting nesfatin-1." (PMID 34361082, 2021). "It is unclear, however, whether 5-HT2CRs are actually expressed on NUCB2 neurons in the hypothalamus and whether NUCB2 contributes to the anorexia induced by 5-HT2CR activation." (PMID 35163521, 2022). "The authors suggest that the induction of Nucb2 in the PVN could play a primary role in promoting the tumor-induced anorexia response of the host." (PMID 34073612, 2021). "Serotonin systems (5-HT1A) could upregulate the expression of NUCB2, a hypothalamic peptide with anorexigenic effect, and induce anorexia." (PMID 21390334, 2011). "Furthermore, when NUCB2 is proteolytically transformed into nesfatin-1, it can stimulate anorexia." (PMID 36678225, 2023). "Although these data do not define a precise role of AVP in anorexia, we hypothesized that AVP-induced nesfatin-1/NucB2 feeding suppression observed in the present study was affected by two distinct pathways." (PMID 34134629, 2021).
polycystic ovary syndrome (13 papers, 2017 to 2026). A disorder that manifests as multiple cysts on the ovaries. "Effects of FF inclusion on oocyte maturation have led to the idea that NUCB2/Nesfatin-1 levels may be associated with ovarian dysfunction, such as oligo/anovulation, polycystic ovaries in PCOS patients." (PMID 31897389, 2019). "The relationships between metabolic alterations and NUCB2/Nesfatin-1 levels were explored in patients with polycystic ovary syndrome (PCOS) undergoing in vitro fertilization/intracytoplasmic sperm injection." (PMID 31897389, 2019).
colon cancer (12 papers, 2016 to 2025). "Therefore, the expression of NUCB-2 in tumor tissue may serve as a biomarker for predicting metastatic risk in colon cancer." (PMID 27150059, 2016). "Knockdown of NUCB2 in the colon cancer cell line SW620 has been shown to reduce migration and invasion." (PMID 40964608, 2025). "Recent studies have shown that NUCB2 is overexpressed in breast, bladder, prostate, clear renal cell carcinoma, ovarian, thyroid, endometrial, gastric, and colon cancer cells compared to that in normal tissue." (PMID 36012443, 2022). "Suppression of NUCB2/NESF-1 in colon cancer cells resulted in morphological changes in the clones, which suggested that NUCB2/NESF-1 was involved in the EMT phenomenon." (PMID 34361082, 2021). "In this study, NUCB-2 knockdowned colon cancer cells showed activation in AMPK pathways and inhibition in TORC1 pathways." (PMID 27150059, 2016). "In this study, we firstly demonstrated that nesfatin-1/NUCB-2 enhances cell migration and invasion in colon cancer." (PMID 27150059, 2016). "Suppression of NUCB-2 inhibited tumor nodule formation in a mouse colon cancer model." (PMID 36718454, 2023). "Additionally, it was shown that the inhibition of NUCB2/NESF1 expression in colon cancer cells suppressed the epithelial-mesenchymal transition (EMT)-related molecules, including N-cadherin, E-cadherin, and β-cadherin as well as EMT properties." (PMID 36012443, 2022). "Additionally, immunohistochemistry showed the expression of NUCB2/NESF-1 in 251 colon cancer patients in relation to clinicopathological properties." (PMID 34361082, 2021). "As the knockdown of Nucb2 in the lymph node metastases of SW620 colon cancer cells leads to the modulation of their shape, this might suggest the involvement of Nucb2 in the EMT." (PMID 34073612, 2021). "The energy stress might be a factor to control AMPK/TORC1 pathways in NUCB-2 knockdowned colon cancer cells." (PMID 27150059, 2016). "It indicates NUCB-2 enhances migration and invasion in colon cancer cells." (PMID 27150059, 2016). "Suppression of NUCB-2 in a colon cancer cell line SW620 inhibited migration and invasion." (PMID 27150059, 2016). "After determining the role of nesfatin-1/NUCB-2 in clinical tumor samples, serum samples, a cell line, an animal tumor model, and an online microarray dataset, our results indicated nesfatin-1/NUCB-2 was a potential biomarker for prediction of metastasis in colon cancer." (PMID 27150059, 2016). "Suppression of NUCB-2 inhibited tumor nodules formation in a murine colon tumor model as well." (PMID 27150059, 2016). "It indicates that NUCB-2 plays a critical role in colon cancer." (PMID 27150059, 2016). "Thus, Nucb2 mediates the EMT in colon cancer cells through the ZEB1, Twist, and Slug pathways." (PMID 34073612, 2021). "Hence, Nucb2 participates in colon cancer cell and LUAD metastasis through EMT induction." (PMID 34073612, 2021). "However, the role of NUCB2 is not well known in colon cancer." (PMID 27150059, 2016). "Some studies have demonstrated that Nesfatin-1/Nucleobindin-2 can suppress the expression of E-cadherin and increase the expression of N-cadherin and Vimentin, thereby inducing migration, invasion, and EMT of colon cancer cells." (PMID 38571500, 2024). "In colon cancer, NUCB-2/nesfatin-1 enhanced migration, invasion and EMT through LKB1/AMPK/TORC1/ZEB1 pathways in vitro and in vivo." (PMID 37635259, 2023). "Studies have shown that the LKB1/AMPK/mTORC1 pathway is involved in nesfatin-1/nucleobindin-2 (NUCB-2)–mediated EMT in colon cancer, and ZEB-1 is critical for regulation of NUCB-2-mediated migration and invasion." (PMID 31126310, 2019). "In colon cancer, the shape of SW620 was changed from spindle shape to rounded shape and migration and invasion ability was inhibited after suppression of NUCB-2." (PMID 27150059, 2016). "The results suggested that AMPK and TORC1 pathways are involved in NUCB-2 regulated EMT properties, migration and invasion in colon cancer." (PMID 27150059, 2016).